DIO3 (iodothyronine deiodinase 3)
Description:
Plays a crucial role in the metabolism of thyroid hormones (TH) and has specific roles in TH activation and inactivation by deiodination. Catalyzes the deiodination of L-thyroxine (T4) to 3,3',5'-triiodothyronine (rT3), 3,5,3'-triiodothyronine (T3) to 3,3'-diiodothyronine (3,3'-T2), 3,5-diiodothyronine (3,5-T2) to 3-monoiodothyronine (3-T1), rT3 to 3',5'-diiodothyronine (3',5'-T2) and 3,3'-T2 to 3'-monoiodothyronine (3'-T1) via inner-ring deiodination (IRD). Catalyzes the deiodination of 3-T1 to L-thyronine (T0) via outer-ring deiodination (ORD). Catalyzes the tyrosyl ring deiodinations of 3,3',5,5'-tetraiodothyronamine, 3,3',5'-triiodothyronamine, 3,5,3'-triiodothyronamine, 3,5-diiodothyronamine, 3,3'-diiodothyronamine and 3-iodothyronamine.
Synonyms: TXDI3; 5DIII; D3; DIOIII
Tractability: Small molecule: it belongs to a druggable protein family. Antibody: UniProt places it where antibodies can reach, with high confidence; its Gene Ontology location is reachable by antibodies, with high confidence; UniProt predicts a signal peptide or a membrane-spanning region.
Target class: Enzyme; Oxidoreductase
Safety:
Unwanted effects reported when the protein is acted on. In parentheses: how it was acted on, where the effect was seen, and who reports it.
Altered, Amphibian metamorphosis (inhibition; source: AOP-Wiki)
Gene: Protein-coding gene on chromosome 14 (101,560,139 to 101,563,452, forward strand). Ensembl gene ENSG00000197406.
Subcellular location: Cell membrane; Endosome membrane
Subcellular location (Human Protein Atlas): Vesicles
Pathways (Reactome):
Metabolism: Regulation of thyroid hormone activity
Gene Ontology:
Molecular function: thyroxine 5-deiodinase activity; thyroxine 5'-deiodinase activity
Biological process: thyroid hormone catabolic process; thyroid hormone metabolic process; brown fat cell proliferation; response to hypoxia
Cellular component: plasma membrane; endosome membrane
Genetic constraint (gnomAD): Loss-of-function variants: 5 observed, 19.57 expected, observed/expected ratio (o/e) 0.26, 90% interval 0.13 to 0.54. The upper end of that interval is the gene's LOEUF score, 0.54, which puts it in group 2 of 6, group 1 being the genes least tolerant of losing a copy. Missense variants: 341 observed, 439.42 expected, observed/expected ratio (o/e) 0.78, 90% interval 0.71 to 0.85. Synonymous variants: 201 observed, 201.48 expected, observed/expected ratio (o/e) 1, 90% interval 0.89 to 1.12.
Homologues: Orthologues: rat Dio3 (95% identical), mouse Dio3 (95% identical), pig DIO3 (89% identical), rabbit DIO3 (57% identical), tropical clawed frog dio3 (25% identical). Paralogues in human: DIO2 (30% identical), DIO1 (29% identical).
Diseases named in the same sentence as DIO3 in open-access papers:
DIO3 is named in the same sentence as 123 diseases in open-access papers, as found by Europe PMC text mining. Sharing a sentence is not in itself a finding about the gene and the disease. The quoted sentences say what the papers report.
hypothyroidism (12 papers, 2012 to 2024). Abnormally low levels of thyroid hormone. "An up-regulation of Dio3 activity as a possible cause of a local condition of hypothyroidism in the decompensated heart, was first observed in a mouse model of right ventricle pathological hypertrophy induced by pulmonary arterial hypertension." (PMID 35742991, 2022). "We observed in mutants that Dio3 mRNA and enzyme activity was elevated in the late-gestation placenta, causing hypothyroidism of the TGMAT embryo and placenta that persisted at birth." (PMID 22326222, 2012). "The connection of olfactory receptors with hypoxia, which is known to increase the expression of type 3 deiodinase (DIO3), could partly explain the association of hypothyroidism with preeclampsia because its pathophysiology is similar to Nonthyroid Illness Syndrome (NTIS)." (PMID 38069004, 2023). "Local hypothyroidism is consistent with the differential expression of pancreatic deiodinases: low Dio1 (0.3 ± 0.07 vs. 1.4 ± 0.2) and high Dio3 (2.4 ± 0.7 vs. 0.8 ± 0.2)." (PMID 37834351, 2023). "Differently from mice, the detected hypothyroidism has been suggested by the inhibition of Dio3 transcripts beyond the increment of Dio1 and Dio2 mRNAs." (PMID 36769379, 2023). "For instance, a loss of Grf1 or Dlk1 resulted in reduced GH content and secretion, while disruption of the imprinting domain encompassing Dlk1, Rtl1, and Dio3 resulted in transient perturbation in the GH/IGF-1 growth pathway with hypothyroidism." (PMID 35025875, 2022). "A number of studies from our laboratory have shown that LV functional improvement and altered Dio3, MCT10 and fetal genes are intimately linked to each other in DM, hypertension, or hypothyroidism and TH treatment of rats reverse these abnormalities." (PMID 26981865, 2016). "LRRK2 deficiency can also be directly linked, via PRDX3, to the potential dysregulation of iodothyronine deiodinase, type III (DIO3), plausibly leading to hypothyroidism via conversion of T4 and T3 to inactive derivatives." (PMID 23799078, 2013). "We have previously reported that complete paternalization of chromosome 12 in uniparental disomy conceptuses results in fetal hypothyroidism due to Dio3 overexpression." (PMID 22326222, 2012). "Interestingly, an increased expression of DLK1 and DIO3 was observed in a large intrathoracic tumor of a patient who developed consumptive hypothyroidism." (PMID 33435319, 2021).
hepatocellular carcinoma (9 papers, 2015 to 2024). A malignant tumor that arises from hepatocytes. "In liver disease, decreased Dio1 expression and activity has been observed in inflammation, fibrosis, and hepatocellular carcinoma, whereas increased Dio3 has been observed in fibrosis." (PMID 36892852, 2023).
myocardial infarction (9 papers, 2014 to 2025). Gross necrosis of the myocardium, as a result of interruption of the blood supply to the area, as in coronary thrombosis. "In a model of myocardial infarction, Dio3 expression is associated with the induction of a pluripotency microRNA signature from the Dlk1-Dio3 genomic region, suggesting a reciprocal association between the expression of paternal Dio3 expression and maternal microRNAs." (PMID 29921775, 2018). "Based on a previous study, although Dio3 was strongly induced in the heart tissues of mice that underwent myocardial infarction, little alteration in T3 levels was detected." (PMID 39877839, 2025). "Myocardial infarction (MI)-induced cardiac stress results in the activation of Dio3, leading to a reduced level of cardiac T3, which in turn, stimulates miR-214 expression." (PMID 29093516, 2017). "In a myocardial infarction (MI) mouse model, Dio3 is up-regulated in cardiomyocytes to create a local hypothyroid condition to increase the regenerative capacity by initiating the fetal gene program." (PMID 28331574, 2017). "In the present study, we investigated the involvement of microRNAs (miRNAs) in the regulation of Dio3 mRNA expression in the remodeling left ventricle (LV) of the mouse heart following myocardial infarction (MI)." (PMID 27014189, 2016). "In addition, we and others have shown that increased cardiac activity of the TH inactivating enzyme, Dio3, results in a local hypothyroid condition in the pathologically remodeled heart due to pressure overload or following myocardial infarction." (PMID 25368602, 2014).
Obesity (8 papers, 2016 to 2024). Accumulation of substantial excess body fat. "For example, higher expression of the paternally expressed imprinted gene DIO3 is associated with diet-induced obesity in mice, and higher expression of the paternally expressed imprinted gene DLK1 is associated with higher levels of white fat in humans." (PMID 37928960, 2023). "Thyroid hormone excess secondary to global type 3 deiodinase (DIO3) deficiency leads to increased locomotor activity and reduced adiposity, but also to concurrent alterations in parameters of the leptin–melanocortin system that would predict obesity." (PMID 36581316, 2023). "The findings of the present study showed that after 8 weeks, NAC significantly reduces the expression of DIO3 gene in the visceral fat tissue of individuals with obesity compared to placebo." (PMID 38702594, 2024). "The obesity phenotype of EF females suggested abnormalities in energy balance that might be a consequence of altered programming of the leptin-melanocortin system, as previously shown for their Dio3-/- fathers." (PMID 37560296, 2023). "Moreover, obesity induces hypomethylation of DIO3 promoter and its upregulation, consistently." (PMID 36320063, 2022). "So that the disruption in DIO2 and thyroid hormone receptors (THRα) gene, unlike DIO3 gene, caused a decrease in fat metabolism along with an increase in insulin resistance and visceral obesity, which indicates the beneficial function of this deiodinase to prevent the development of obesity." (PMID 38702594, 2024). "Our findings suggest that obesity may alter expression of THRB and DIO3 genes through epigenetic mechanism." (PMID 36320063, 2022).
schizophrenia (7 papers, 2014 to 2024). A major psychotic disorder characterized by abnormalities in the perception or expression of reality. "We have recently described that the sperm DNA of Dio3−/− mice, which are overexposed to thyroid hormone during development, exhibit a decreased in methylation in the promoter region of genes associated in humans with susceptibility to neurodevelopmental disorders such as autism and schizophrenia." (PMID 36419462, 2022). "Examples include genes from the IGF2-H19 imprinted locus on chromosome 11p15, e.g., IGF2, H19, and miR483, and DLK1, DIO3, and miR134, which reside within the DLK1-DIO3 imprinted locus at 14q32 and whose misregulation is linked to schizophrenia and bipolar disorder." (PMID 35440587, 2022).
breast carcinoma (5 papers, 2017 to 2023). "In breast cancer, reduced DIO3 expression is associated with decreased overall survival." (PMID 32807826, 2020). "Here, we investigated the patterns of DIO3 expression and its prognostic significance in breast cancer." (PMID 32807826, 2020). "DIO3 expression was evaluated by immunohistochemistry in a primary cohort of patients with breast cancer and validated in a second cohort using RNA sequencing data from the TCGA database." (PMID 32807826, 2020). "Here, we demonstrate that the TH-inactivating enzyme DIO3 is expressed in normal breast tissue and that its expression is highly prevalent in breast cancer." (PMID 32807826, 2020). "In conclusion, DIO3 is expressed in normal and tumoral breast tissue, while decreased expression relates to poor overall survival in breast cancer patients." (PMID 32807826, 2020). "Although this was an exploratory study, our results point to a prognostic role for DIO3 expression in breast cancer." (PMID 32807826, 2020). "Considering the implied role of the DIO3 gene in human neoplasms and the potential effect of TH in breast carcinogenesis, we investigated the expression patterns of DIO3 in normal breast tissue and breast cancer." (PMID 32807826, 2020). "Here, we demonstrate that DIO3 is expressed in normal breast tissue and breast cancer tissue." (PMID 32807826, 2020).
lupus (4 papers, 2016 to 2023). "Further study is needed to determine the genes and signaling pathways that are targeted by these dysregulated Dlk-Dio3 miRNAs in lupus cells, which is important for understanding the mechanism of Dlk1-Dio3 miRNAs in SLE pathogenesis." (PMID 34062726, 2021).
thyroid cancer (4 papers, 2017 to 2025). "Loss of DIO3 expression was associated with tumor aggressiveness in colon cancer and also in thyroid cancer." (PMID 32807826, 2020).
thyrotoxicosis (4 papers, 2014 to 2025). A hypermetabolic syndrome caused by the elevation of thyroid hormone levels in the serum. "In addition, DIO3 involved in the inactivation of thyroid hormones may preferentially be expressed from the paternal allele, and Dio3 knockout mice manifest thyrotoxicosis, color blindness, and hearing loss." (PMID 39693239, 2025). "To delineate the deleterious craniofacial and cardiac abnormalities that may arise in utero from maternal hyperthyroidism, here we study a mouse model of physiological and persistent developmental thyrotoxicosis secondary to a deficiency in the type 3 deiodinase (DIO3)." (PMID 36166296, 2022). "Although the molecular and physiological mechanisms underlying each of these defects remain to be elucidated, our results demonstrate a critical role for Dio3 in protecting the embryo from thyrotoxicosis, starting early in development." (PMID 36166296, 2022). "The expression of T3-regulated genes, including Hr, Dio1, Gpd2, Dbp, and Klf9, was markedly elevated in Dio3–/– fetuses compared with Dio3+/+ littermates, indicating thyrotoxicosis in all tissues." (PMID 36166296, 2022). "Here we show that, as expected, Dio3–/– mouse fetuses experienced profound and systemic thyrotoxicosis in late gestation." (PMID 36166296, 2022). "To address this issue, we studied a mouse model of comprehensive developmental thyrotoxicosis secondary to a lack of type 3 deiodinase (DIO3)." (PMID 36166296, 2022).
Anxiety (3 papers, 2012 to 2021). Intense feelings of nervousness, tension, or panic often arise in response to interpersonal stresses. "Additional behavioral assays would be required to firmly associate Dio3 expression with anxiety-like behavior, but our current data indicate the proof-of-concept that LB rats behaved differently from BL rats on a classic, stable measure of anxiety: time spent in the periphery of the open field." (PMID 23248649, 2012). "Here, we tested the hypothesis that genetic polymorphisms between the SD and BN parent strains cause this aberrant allelic Dio3 expression and contribute to behavioral sequelae of higher thyroid hormone levels locally in the hippocampus, including anxiety-related behavior." (PMID 23248649, 2012). "Dio3−/− mice of both sexes manifest hyperactivity and reduced anxiety-and depression-like behaviors." (PMID 29921775, 2018). "Deletion of the miR-379/miR-410 gene cluster at the imprinted domain enhances anxiety-related behavior, in contrast with the decreased anxiety-related behavior observed in Dio3−/− mice." (PMID 29921775, 2018). "Our data is consistent with the idea that Dio3 is one of many genes which by small variations in its expression, affects brain circuits that control complex, multigenic behaviors including anxiety-like behavior." (PMID 23248649, 2012). "Previously, SB animals showing maternal hippocampal Dio3 expression exhibited anxiety-like behaviors compared to the reciprocal BS cross." (PMID 23248649, 2012). "The resulting sequelae included a higher level of T3 in the hippocampus (as the Dio3 enzyme is responsible for inactivating thyroid hormones) and several anxiety-related behaviors." (PMID 23248649, 2012). "Interestingly, Dio3-/- mice, which have elevated TH, exhibit multiple behavioral abnormalities, including reduced anxiety and depression." (PMID 34257897, 2021). "We confirmed this novel pattern of expression using a different reciprocal cross harboring the same genetic differences in the promoter region of Dio3, indicating that parent-of-origin Dio3 expression in the hippocampus is of genetic origin, and confirmed the co-occurrence of anxiety-like behavior." (PMID 23248649, 2012). "Although these patients also exhibit mild mental retardation, no abnormalities have been reported in relation to anxiety, depression, aggressive behavior or hyperactivity, as those manifested by Dio3−/− mice." (PMID 29921775, 2018).
autism (3 papers, 2022 to 2024). Persistent deficits in social interaction and communication and interaction as well as a markedly restricted repertoire of activity and interest as well as repetitive patterns of behavior. "Also, the imprinted gene Dio3 in male pups, while H19 and Xist in female pups, were upregulated by high gestational folic acid supplementation, accompanied by different expressional changes in the candidate autism susceptible gene Auts2 between male and female pups." (PMID 36386900, 2022).
hyperthyroidism (3 papers, 2014 to 2022). Overactivity of the thyroid gland resulting in overproduction of thyroid hormone and increased metabolic rate. "Positive gene such as Hr, Kcnj10, Shh, and others were not affected by Dio3 inactivation but were sensitive to T3-induced hyperthyroidism." (PMID 24618783, 2014).
papillary thyroid carcinomas (3 papers, 2021 to 2024). "Others have also suggested that the MAPK and SHH pathways modulate DIO3 expression in papillary thyroid carcinomas and in an MTC cell line." (PMID 33435319, 2021).